MYC (MYC proto-oncogene, bHLH transcription factor)
Diseases named in the same sentence as MYC in open-access papers (continued):
Sharing a sentence is not in itself a finding about the gene and the disease.
triple-negative breast carcinoma (155 papers, 2013 to 2026). An invasive breast carcinoma which is negative for expression of estrogen receptor (ER), progesterone receptor (PR), and human epidermal growth factor receptor 2 (HER2). "Intriguingly, BBOX1’s upregulation is not limited to PDAC but extends to triple-negative breast cancer, a disease that is also known to be intricately linked to MYC activation." (PMID 37980563, 2023). "We previously demonstrated that MYC regulates polyamine metabolism in triple-negative breast cancer (TNBC) and that a plasma polyamine signature is associated with TNBC development and progression." (PMID 33671595, 2021). "Overexpression of MYC oncogene is highly prevalent in many malignancies such as aggressive triple-negative breast cancers (TNBCs) and it is associated with very poor outcome." (PMID 30076412, 2019). "MYC is one of the most powerful oncogenes and is known to be associated with triple-negative breast cancer (TNBC)." (PMID 31905596, 2019). "Hypoxanthine-guanine-(xanthine) phosphoribosyltransferase [HG(X)PRT] is an excellent target for the development of new drugs to treat parasitic and bacterial infections as well as MYC-dependent triple-negative breast cancer." (PMID 40844434, 2025). "The MYC proto-oncogene is upregulated in >60% of triple-negative breast cancers (TNBCs), it can directly promote tumor cell proliferation, and its overexpression negatively regulates anti-tumor immune responses." (PMID 39706891, 2025). "Another circUBR5 was recently reported (2024) to promote ribosome biogenesis and docetaxel resistance in triple-negative breast cancer via the miR-340-5p/CMTM6/c-MYC axis." (PMID 40806254, 2025). "A PROTAC based on TNA (threose nucleic acid) and DNA has been developed to effectively target and degrade MYC in triple-negative breast cancer cells, which provides a promising therapeutic intervention for triple-negative breast cancer." (PMID 40290126, 2025). "Here, we show that Omomyc, the only direct MYC inhibitor that has completed a phase 1 trial, shuts down DDR genes in triple-negative breast cancer (TNBC), causing DDR defects and inducing DNA damage." (PMID 41273720, 2025). "In triple-negative breast cancer, the oncogenic transcription factor MYC is abnormally increased, activating cellular FAO to promote cell proliferation." (PMID 38698462, 2024). "In previous reported that inhibition of fatty acid oxidation as a therapy for MYC-overexpressing triple-negative breast cancer." (PMID 39834541, 2024). "The in vivo data strongly suggests that this new drug is therapeutically effective in inhibiting c-MYC-driven triple-negative breast cancer and metastatic tumors." (PMID 39123391, 2024). "STTs cause widespread cytoplasmic accumulation of mis-spliced mRNAs, many forming double-stranded structures in MYC-driven triple-negative breast cancer." (PMID 39190284, 2024). "In the metastatic triple-negative breast cancer (mTNBC) population, we observed a focal amplification of MYC (16.3%) and a homozygous deletion of PTEN (9.7%) as the more common CNA events." (PMID 39090361, 2024). "SPAG5 interacts with MYCBP to elevate the transcriptional activity of c-MYC, thereby accelerating DNA repair and tumor growth of triple-negative breast cancer." (PMID 38807081, 2024). "A combination of MYC blockade with PARPi yielded synthetic lethality in MYC-driven triple-negative breast cancers, indicating a potential treatment opportunity for future clinical trials in AOC." (PMID 39591206, 2024). "MYC is an oncogenic driver of tumor development, progression, and immune-suppression in triple-negative breast cancer (TNBC)." (PMID 37046602, 2023). "A c-MYC deregulation is frequently involved in the carcinogenesis of lymphoblastic leukemia and triple-negative breast cancer." (PMID 37570631, 2023).
triple-negative breast carcinoma (continued). "MYC was recently reported to promote immune-suppression in triple-negative breast cancer via inhibition of STING-IFN-I signaling in a tumor cell-intrinsic fashion via direct transcriptional repression." (PMID 37898690, 2023). "In triple-negative breast cancer, high IGF2BP2 expression is associated with cancer cell migration and invasion and promotes the stability of MYC mRNA." (PMID 35915142, 2022). "Of note, SNHG12 is a downstream target gene of the oncoprotein MYC and its upregulation mediates cell proliferation and migration in triple-negative breast cancer." (PMID 35406435, 2022). "Further empirical studies have revealed that MYCBP interacts with SPAG5 enhancing c-MYC transcriptional activity in triple-negative breast cancer." (PMID 34277412, 2021). "Meanwhile, this imaging modality was demonstrated to define the MYC status in other tumor entities, like triple negative breast cancer models and allows monitoring of treatment induced changes of MYC expression." (PMID 34637026, 2021). "MCF-10A cells overexpressing MYC have been proposed to be a cellular model for triple negative breast cancer." (PMID 34676047, 2021). "While c-MYC was shown to induce the IRE1-XBP1s pathway in a triple-negative breast cancer model, UPR/XBP1s can also directly activate MYC expression." (PMID 33746610, 2021). "Repression of the miR-200b/200a/429 promoter by MYC was documented in endometrial cancer cells and in triple-negative breast cancer cells." (PMID 34884985, 2021). "Independent of hnRNPC targeting, a recent study described spliceosome inhibition in triple-negative breast cancer with MYC-driven hyperactivated transcriptional activity." (PMID 34297039, 2021). "Targeting the MYC gene provides a new research direction for the treatment of triple-negative breast cancer." (PMID 34993016, 2021). "Recently, MUC1-C was found to activate PD-L1 transcription by recruiting MYC and NF-κB to the PD-L1 promoter region in triple-negative breast cancer." (PMID 35069587, 2021). "The poor survival of triple-negative breast cancer patients correlates with elevated c-MYC and decreased expression of TXNIP, which is probably due to c-MYC binding to the TXNIP promoter." (PMID 33228209, 2020). "Recent studies have suggested that fatty acid oxidation (FAO) is a key metabolic pathway for the growth of triple negative breast cancers (TNBCs), particularly those that have high expression of MYC." (PMID 31942031, 2020). "Molecular profiling of tumor cells persisting after neo-adjuvant chemotherapy for triple-negative breast cancer showed amplifications of MYC(54%) and MCL-1(35%)." (PMID 33308268, 2020). "In Triple Negative Breast Cancer, coupled with MYC, DNMT3a promotes the epithelial to mesenchymal transition and mammosphere formation of TNBC cells by upregulating miR-200b promoter methylation." (PMID 33234142, 2020). "In triple-negative breast cancer, MYC overexpression correlates with an increased dependency on mitochondrial FA oxidation." (PMID 31856871, 2019). "MYC inhibition depletes cancer stem-like cells in triple-negative breast cancer, and the central role of c-Myc is the regulation of proliferation and survival of glioma cancer stem cells." (PMID 30149665, 2018). "SNHG12 is induced by c-MYC and regulates cell proliferation, apoptosis, and migration in triple negative breast cancer." (PMID 29757368, 2018). "Similar dependency on fatty acid oxidation was recently reported in MYC-overexpressing triple-negative breast cancer cells." (PMID 28415728, 2017). "Recently, targeting fatty acid oxidation has shown decreased tumor growth in an in vivo model of MYC-driven triple negative breast cancer." (PMID 28487492, 2017). "It has been recently reported that in a MYC-driven triple-negative breast cancer model, inhibition of fatty acid oxidation function through a MYC-mediated mechanism suppressed the growth of MYC-overexpressing cells." (PMID 28362357, 2017).
triple-negative breast carcinoma (continued). "Our data, which revealed a upregulation of AXIN2, DKK1 and MYC in the TamR cells, are largely consistent with findings documented in current literature on triple negative breast cancer." (PMID 23547709, 2013). "However, recent identification of CIP2A as a central DNA damage response (DDR) protein essential for BRCA-mutated triple-negative breast cancer (TNBC) cells, indicates that CIP2A has broader role in cancer beyond MYC regulation." (PMID 36854761, 2023). "Moreover, leveraging the acridone scaffold opens avenues for designing more compounds targeting c-MYC’s G4 structure, thereby providing additional potential options for treating triple-negative breast cancer." (PMID 38275631, 2023). "Notably, the N-8 compound exhibited the most significant activity and demonstrated a high degree of selectivity for the G4 structure of the c-MYC gene, presenting itself as a promising candidate for a novel therapy for triple-negative breast cancer." (PMID 38275631, 2023). "MYC is one of the most frequently altered driver genes in triple-negative breast cancer (TNBC)." (PMID 35908121, 2022). "FAO inhibition can reduce the energy metabolism and suppress tumorigenesis in MYC‐high expressed triple negative breast cancer (TNBC), suggesting that MYC could serve as a biomarker for determining which patients may benefit from FAO inhibition therapy." (PMID 34766135, 2021). "In triple-negative breast cancer cells, binding of MYC to the miR-200b/200a/429 promoter leads to recruitment of DNMT3A to promoter CpGs, resulting in promoter methylation; negative feedback control is provided by direct targeting of the DNMT3A mRNA by miR-200b." (PMID 34884985, 2021). "Also, MYC gene is overexpressed in triple-negative breast cancer and targeting the gene provides a new treatment." (PMID 34567213, 2021). "Interestingly, MCL-1 in cooperation with MYC induced drug resistance in triple-negative breast cancer via upregulation of mitochondrial oxidative phosphorylation and expansion of cancer stem cells." (PMID 33308268, 2020). "Upregulation of MYC has been reported in many triple-negative breast cancer (TNBC) cells." (PMID 32225100, 2020). "Recent data have shown how ATF4, MYC and mTORC1 stress-response pathways may converge in cancers that are reliant on glutamine, such as triple-negative breast cancer, where oncogenic MYC is a suspected driver of glutamine-reliance." (PMID 29940911, 2018). "Importantly, MYC is found to bind to and regulate SOX2 gene expression in CSCs derived from triple negative breast cancer, suggesting MYC can regulate cancer stemness by modulating the expression of other critical embryonic stem cell markers such as Sox2." (PMID 27821172, 2016). "In addition, mir-873-5p could regulate triple-negative breast cancer cells’ proliferation and metastasis by inhibiting the MYC proto-oncogene, bHLH transcription factor." (PMID 38693503, 2024). "Moreover, the depletion of circCD44 or IGF2BP2 affects the levels of m6A-modified c-MYC mRNA, suggesting that the interaction between circCD44 and IGF2BP2 may stabilize c-MYC in triple-negative breast cancer (TNBC)." (PMID 39596216, 2024). "Moreover, CDK1 may interfere with the synthetic lethality of other oncogenes, such as MYC in triple-negative breast cancer, PARP and PI3-kinase." (PMID 32948832, 2021). "In triple-negative breast cancer, high expression of XPO1 accelerates proliferation by exporting oncogene mRNAs such as MYC and ERBB2, inhibits mitochondrial release of Cyt c, and weakens apoptotic sensitivity." (PMID 40860340, 2025). "PAL, when combined with olaparib, inhibited Wnt/β-catenin signaling—specifically by reducing β-catenin Ser675 phosphorylation and MYC expression—thereby reversing EMT and overcoming olaparib resistance in triple-negative breast cancer." (PMID 40569965, 2025). "MYC also raises the expression of POLR3G, a pol III subunit that promotes tumour growth and metastasis in triple-negative breast cancer." (PMID 37509247, 2023).
triple-negative breast carcinoma (continued). "Functionally, CRISPR/Cas9-mediated single amino acid mutagenesis of the head domain blunted MYC expression and MEK phosphorylation, and abrogated triple-negative breast cancer in vivo tumour growth." (PMID 36854761, 2023). "Knocking down SPAG5 increased the S-phase cell population and decreased the expression of c-MYC target genes, including the DNA repair proteins RAD51 and BRCA1/2 in triple-negative breast cancer." (PMID 36304306, 2022). "In triple-negative breast cancer, MUC1-C increases PD-L1 transcription and promotes tumor immune escape by recruiting MYC and NF-κB p65 to the PD-L1 promoter region." (PMID 35879749, 2022). "For instance, MYC and DNMT3A-mediated DNA methylations on the miR-200b promoter repress triple negative breast cancer migration, invasion, and cancer stem cell-like properties." (PMID 35860691, 2022). "In triple-negative breast cancer (TNBC), MYC was found to regulate polyamine metabolism and a plasma polyamine signature was related to the development and progression of TNBC." (PMID 35771747, 2022). "In contrast, super-enhancers found in triple-negative breast cancer (ER−, PR−, HER2−) co-localized with the transcription factors FOXC1, MET, MYC, and ANLN." (PMID 36232979, 2022). "Co-occurrence of amplifications in MYC and genes from the PI3K pathway is independently observed in squamous lung cancer and triple negative breast cancer." (PMID 36289203, 2022). "As a model, we used the invasive, human triple negative breast carcinoma cell line, MDA-MB-231T, which was stably transfected either by FLAG::NME1 or MYC::NME2 or the control vector." (PMID 36010906, 2022). "Previously, a study report has decoded that MYC interacts with DNMT3a, thus silencing miR-200b and leading to EMT in triple-negative breast cancer." (PMID 34623601, 2022). "The same observation was made in SUM149 and SUM159 triple negative breast cancer cells; the sensitivity to AOA was further found to be specific to MYC-active cells." (PMID 34503295, 2021). "In addition, Astrin was found to interact with MYCBP to promote the transcriptional activity of c-MYC, which could promote cell proliferation via upregulating c-MYC targeted genes including CDC20, CDC25C, breast-cancer susceptibility gene (BRCA) 1, and BRCA2 in triple-negative breast cancer." (PMID 32984344, 2020). "A second study from the same group reported that triple-negative breast cancer (TNBC) with elevated MYC expression displayed efficacy with CDK1 inhibition (purvalanol, dinaciclib, or siRNA), compared to lines with low MYC expression." (PMID 33322239, 2020). "In triple-negative breast cancer, where MYC is frequently amplified, especially in BRCA mutant tumors, the CDK inhibitor dinaciclib downregulated MYC as well as HR genes and sensitized PARPi-resistant cells to PARPi38, opposite to our Myc results in GSCs." (PMID 31266951, 2019). "Another study demonstrated that c-MYC-induced SNHG12 upregulation promoted cell proliferation and suppressed apoptosis in triple-negative breast cancer." (PMID 29137407, 2017). "c-MYC is overexpressed in 70% of human cancers, including triple-negative breast cancer (TNBC), yet there is no clinically approved drug that directly targets it." (PMID 39123391, 2024). "We also observed a correlation between the expression levels of ADSL and the MYC oncogene, whose expression has been shown to be indirectly regulated by ADSL in triple-negative breast cancer 6 and whose upregulation of target genes is a signature of the CMS2 subtype 37." (PMID 33754045, 2021). "Given that ADSL-overexpressing Caco-2 cells displayed a significant enrichment for MYC-targets and that ADSL was previously shown to activate the c-MYC pathway in triple negative breast cancer 6, we therefore asked whether a similar mechanism occurs in CRC." (PMID 33754045, 2021).
triple-negative breast carcinoma (continued). "Interestingly, MYC was upregulated in ALDH1-enriched mammosphere cells from cell lines and triple-negative breast cancers; this was seen also in CD44-expressing cells." (PMID 31661927, 2019). "MYC activation downstream of ERK in human triple negative breast cancer activates a negative feedback loop that downregulates several tyrosine kinase receptors, which impacts on RAS/MAPK/AKT signaling." (PMID 30526305, 2018). "This is also consistent with another study in triple-negative breast cancer that TXNIP level is inversely correlated to MYC level, whereby MYC could repress expression of TXNIP." (PMID 29996811, 2018). "Recent studies have shown that sunitinib-mediated VEGFR2 silencing participates in regulating pluripotency in embryonic stem cells and triple-negative breast cancer, and that a stable mesothelioma cell line derived from a patient over-expressing VEGFR2 and c-MYC had stem-like traits." (PMID 27705913, 2016). "Additionally, we examined the role of HMGA1, a non-histone chromatin-related protein that was recently described as a marker overexpressed in MYC-negative triple-negative breast cancer." (PMID 36433941, 2022). "However, triple-negative breast cancer (TNBC), the most aggressive subtype, is not commonly associated with BRD4/MYC regulation." (PMID 31758045, 2019). "Accordingly, we observed elevated levels of MYC protein in a TNBC cell line, MDA-MB-231, compared with non-cancerous MFC10A and non-triple negative breast cancer cells." (PMID 32225100, 2020). "These tumors exhibit elevated c-MYC expression, and the authors used CDK1 siRNA delivered by cationic lipid assisted nanoparticles to induce decreased cell viability and apoptosis only in c-MYC overexpressed triple-negative breast cancers and not in normal mammary epithelial cells." (PMID 28855742, 2017).